RNU2-55P (RNA, U2 small nuclear 55, pseudogene)
Gene: Small nuclear RNA gene on chromosome 21 (23,281,736 to 23,281,909, reverse strand). Ensembl gene ENSG00000223078.
Homologues: Orthologues: chimpanzee U2 (79% identical), mouse Gm25052 (40% identical), dog U2 (39% identical), pig U2 (34% identical), dog U2 (34% identical), dog U2 (33% identical), guinea pig U2 (33% identical), rat LOC120097278 (33% identical), pig U2 (32% identical). Paralogues in human: RNU2-28P (43% identical), U2 (43% identical), RNU2-10P (43% identical), RNU2-22P (41% identical), RNU2-59P (41% identical), RNU2-41P (40% identical), U2 (40% identical), RNU2-2 (39% identical), RNU2-4P (39% identical), RNU2-58P (39% identical), RNU2-6P (39% identical), RNU2-23P (39% identical), and 63 more.